MIF (macrophage migration inhibitory factor)
Diseases named in the same sentence as MIF in open-access papers (continued):
Sharing a sentence is not in itself a finding about the gene and the disease.
glioma (continued). "Regarding the primary-recurrent-secondary (PRS) type, ALDOC and ABAT exhibited decreased expression, while MIF and PGK1 showed increased expression in recurrent and secondary glioma groups." (PMID 38989284, 2024). "Consistent with the changes in expression, patients with higher expression of LDHA, MIF, NAMPT, PGK1, SAT1, and PLOD2, and lower expression of ALDOC, ABAT, ADCY2, GALNT13, and PDE8B showed poorer survival rates in all glioma samples." (PMID 38989284, 2024). "In the hypoxic area of glioma specimens, MIF co-localized with CXCR4 where MIF promotes vasculogenic mimicry formation." (PMID 38178143, 2024). "We identified a subgroup of glioma cells with elevated TRIM56 expression, showing increased secretion of VEGF and MIF proteins compared to other subgroups." (PMID 38348047, 2024). "Secreted signals in MAN1C1-expressing glioma cells, such as PTN, MIF, ANXA1, MDK, and NAMPT, allowed MAN1C1 to interact with myeloid/microglial cells." (PMID 39333557, 2024). "As these cells are also sources of MIF and DDT expression, Ibudliast offers promise as a pharmacologic intervention to CNS cancers such as glioblastoma and brain metastases." (PMID 38732068, 2024). "MIF is an important microenvironmental factor in glioma, and we previously identified an immune-suppressive pathway in GBM that is driven by secreted MIF from cancer stem cells (CSCs) that in turn activates myeloid-derived suppressor cells (MDSCs)." (PMID 37252795, 2023). "This close relationship between the expressions of MIF and VEGF was also reported in other types of cancer, such as gliomas." (PMID 36672343, 2023). "Angio-TAMs and LA-TAMs were observed to have shared signaling amongst both glioma types in SPP1 and MIF pathways." (PMID 38012322, 2023). "MIF interacted with CD74 to promote M2 immunosuppressive shift and inhibit M1 polarization, resulting in glioma development." (PMID 36387901, 2022). "In glioma stem cells (GSC), it has been shown that miR-608 negatively regulated MIF expression by direct targeting its 3'UTR." (PMID 29707160, 2018). "The analysis of the in vivo levels of MIF expression in 166 gliomas and 23 normal control brains by immunohistochemistry has shown that MIF immunoreactivity was increased in WHO grade II gliomas and increased significantly in higher tumour grades (III-IV)." (PMID 29707160, 2018). "In particular, it has been demonstrated that upregulation of MIF in glial tumour cells is induced by hypoxic and hypoglycaemic stress and that MIF and CXCR4 colocalize in hypoxic area in glioma specimens." (PMID 29707160, 2018). "Here, we determined that the expression of MIF and CXCR4 was positively correlated with the grade of glioma and the HIF level." (PMID 29113309, 2017). "By analyzing clinical specimens, we observed the co-localization of MIF, C-X-C motif chemokine receptor 4 (CXCR4) and VM in hypoxic regions of gliomas." (PMID 29113309, 2017). "The expression of HIF1α, MIF and CXCR4 in clinical specimens (six normal brain tissues and twenty-five human glioma tissues) was positively correlated with the grade of glioma." (PMID 29113309, 2017). "In this study, we established a previously unrecognized link between VM formation and high co-expression of MIF and CXCR4 within hypoxic regions of glioma specimens." (PMID 29113309, 2017). "We used immunohistochemistry to evaluate the expression of HIF1α, MIF and CXCR4 in our glioma specimens." (PMID 29113309, 2017). "Our attention was particularly drawn to Macrophage Migration Inhibitory Factor (MIF), which was significantly elevated across all three of our glioma conditioned medias." (PMID 28666020, 2017). "With regard to MIF, however, production and secretion of MIF occur in TZ1, while its receptors are mainly expressed by microglial cells in TZ2 and on glioma cells themselves." (PMID 22973314, 2012). "Glioma-myeloid and myeloid-glioma signaling identified EGFR, SPP1, MIF, and other important LRI." (PMID 40191211, 2025).
glioma (continued). "Furthermore, METTL3 suppresses MIF expression by upregulating EIF3J-AS1, thereby inhibiting autophagy in glioma cells." (PMID 41390674, 2025). "Others were robust and shared across most samples such as CD74 receptor binding to MIF, COPA, or APP as cognate ligands and SPP1-CD44 (myeloid to glioma signaling) and TNFRSF1A-GRN, PGRMC2-CCL4L2, MDK-SORL1 or LRP1, and GPR37L1-PSAP (glioma to myeloid signaling)." (PMID 35140215, 2022). "As 4-IPP has previously been shown to induce apoptosis in thyroid carcinoma, we evaluated whether the inhibition of MIF and DDT by 4-IPP also results in enhanced apoptosis in glioma." (PMID 34516577, 2021). "Evaluation of bioinformatics databases has shown significantly higher levels of MIF in GBM compared with non-tumor tissues, and MIF expression has been associated with poor prognoses and early recurrence in association with gliomas." (PMID 34516577, 2021). "Glioma biopsies have increased expression in HIF-1α, MIF, and CXCR4." (PMID 31993365, 2019). "In support of the role played by MIF as immune check-point regulator in GBM, in vitro treatment with the MIF inhibitor, sulforaphane, suppressed the transformation of normal monocytes to MDSCs by glioma-conditioned media." (PMID 29707160, 2018). "Furthermore, a closely positive relationship between VM formation and high co-expression of MIF and CXCR4 was revealed within hypoxic regions of gliomas." (PMID 29113309, 2017). "Our results showed that MIF was necessary for MDSC induction by glioma-conditioned media but not sufficient." (PMID 28666020, 2017). "By inhibiting the expression of macrophage migration inhibitory factor (MIF), it enhances the expression of DRP1 and p-DRP1 while simultaneously inhibiting the expression of OPA1 and MFN2 to promote mitochondrial fission, thereby promoting the progression of glioma." (PMID 40332101, 2025). "However, in this study, we found that oxaliplatin can induce overactivation of PARP1, leading to release of AIF, and then AIF interacted with MIF and was transferred into the nucleus, resulting in parthanatos in OSCC cells, which is similar to a previous study on gliomas." (PMID 33495407, 2021). "Monoclonal anti-MIF antibodies have been tested in experimental models of GBM and have provided significant results, especially in vitro where they were able to considerably reduce the growth of LN18 and LN229 glioma cells with maximal results under confluent culture conditions." (PMID 29707160, 2018). "Interestingly, they found that MIF production was limited to cancer stem cells, not differentiated glioma cells." (PMID 28666020, 2017). "Although the low CD74 expression in the LN18 cells most likely account for the unresponsiveness to exogeneous MIF, a different glioma cell line not expressing CD74 has been found to still be responsive to recombinant MIF - arguing for an alternative MIF receptor." (PMID 20038293, 2009). "In addition, while GCs alone did not suppress Hs683 glioma cells migration and invasion, the combined treatment with ISO-1, at the dose of 1000 μM, and 1μM dexamethasone markedly reduced both parameters, suggesting that MIF blockade can be a way to sensitize glioma cells to GCs effects." (PMID 29707160, 2018).
Obesity (63 papers, 2010 to 2026). Accumulation of substantial excess body fat. "Our current study explores the involvement of MIF in the development of obesity, insulin resistance, and hyperlipidemia caused by other AAPs, including CLZ, APZ, RIS, and QTP, which are commonly prescribed in clinical settings." (PMID 38802393, 2024). "MIF is expressed in mature adipocytes and macrophages and is associated with obesity and insulin resistance." (PMID 38175171, 2024). "Emerging work has shown that circulating MIF levels are significantly elevated in obesity, while weight loss reduces plasma MIF levels." (PMID 37283810, 2023). "EV specific carriers of MIF involved in the development of insulin-resistance associated with diabetes and obesity." (PMID 33477341, 2021). "Several studies demonstrated that MIF played an important role in the development of obesity and the associated diseases including insulin resistance, T2D, cardiovascular disease (CVD) and NAFLD." (PMID 32265835, 2020). "Studies showed that there was a positive association between obesity and serum circulating MIF levels." (PMID 32265835, 2020). "Chronic inflammation, a common risk factor of diabetes and obesity, induced by the proinflammitory action of MIF is associated with insulin resistance and glucose intolerance." (PMID 28230058, 2017). "Another intriguing trend is the dose-dependent increase in MIF, which acts as a pro-inflammatory signal in AT and positively associates with obesity-related insulin resistance." (PMID 27384973, 2017). "Identification of the underlying factors that determine circulating MIF in obesity warrants further investigation." (PMID 26124760, 2015). "Several groups have investigated the role of MIF in obesity and associated development of insulin resistance/T2D using high-fat diet (HFD)-induced rodent models of disease." (PMID 26124760, 2015). "In 2006, Sakaue and coworkers found that −794 CATT5–8 MIF polymorphism was associated with obesity in a Japanese population." (PMID 25972622, 2015). "Several studies provide evidence for a positive association between obesity and circulating MIF levels." (PMID 26124760, 2015). "Increasing evidence suggests that MIF is released by adipose tissue in obesity and that it is also involved in metabolic and inflammatory processes that underlie the development of obesity-related pathologies." (PMID 26124760, 2015). "MIF plays an important role in the chronic, obesity-associated adipose tissue inflammation that leads to the development of insulin resistance in MIF-KO mice." (PMID 24527464, 2014). "This is a comprehensive summary of our current knowledge on the role of MIF in obesity and obesity-associated comorbidities, based on human clinical data as well as animal models of disease." (PMID 20169173, 2010). "This survey summarizes our current knowledge on the role of MIF in obesity-associated comorbidities, based on clinical and research data." (PMID 20169173, 2010). "Increasing evidence suggests that MIF also controls metabolic and inflammatory processes underlying the development of metabolic pathologies associated with obesity." (PMID 20169173, 2010). "Macrophage migration inhibitory factor (MIF) is an innate cytokine involved in many inflammatory and autoimmune disorders; many of these pathologies are associated with obesity including cardiovascular and kidney disease." (PMID 20169173, 2010). "Blocking the extracellular action of MIF by a neutralizing anti-MIF antibody significantly prevented the development of HFD-induced obesity which is associated with reduced adipose AMPK/JNK signaling and reversed HSL in HFD mice, further suggesting a role for extracellular MIF in downregulating HSL." (PMID 37935315, 2024). "Particularly, the expression of MIF has been associated with obesity and its comorbidities." (PMID 38175171, 2024).
Obesity (continued). "The Sakaue study found that haplotypes of both promoter polymorphisms of the MIF gene are associated with obesity, suggesting that increased expression of this gene may be the result of metabolic dysregulation in obesity." (PMID 39330807, 2024). "MIF gene expression in abdominal fat, including visceral and subcutaneous adipose tissue is positively associated with waist circumference or body fat percentage in obesity." (PMID 37283810, 2023). "The pro-inflammatory cytokine, MIF, causes adipose tissue dysfunction, leading to obesity by promoting the release of pro-inflammatory cytokines, adipocyte differentiation, and immune cell infiltration and activation, resulting in inflammation and metabolic dysfunction." (PMID 38111581, 2023). "Based on this study, an interesting hypothesis is that PIP4K2a mediated the phosphorylation of PtdIns5P to generate various phosphoinositide species may contribute to ciliopathies associated obesity, and MIF may be involved in this process." (PMID 38052787, 2023). "Furthermore, associations between MIF genotype Rs1007888GG and gestational diabetes as well as pre-pregnancy obesity and family history of diabetes have been reported." (PMID 26124760, 2015). "However, the direction of the effect (obese higher than lean) is mostly consistent and overall, these studies demonstrate a well-established association between obesity and circulating MIF that seems to transcend differences in age, sex, and ethnicity." (PMID 26124760, 2015). "Relationship between (circulating) MIF and obesity and effects of weight loss thereupon." (PMID 26124760, 2015). "MIF is also associated with multiple disorders, including autoimmunity, obesity and cancer." (PMID 26087187, 2015). "Remarkably, there is a large variation in the absolute circulating MIF values in documented obesity studies, indicating that there may be underlying methodological differences causing these diverse values." (PMID 26124760, 2015). "Since MIF is recognized as a proinflammatory cytokine and obesity is associated with a chronic inflammatory response, MIF may have an impact on the pathophysiology of obesity." (PMID 25972622, 2015). "Increasing evidence suggests that MIF may also control inflammatory and metabolic processes in the pathogenesis of obesity and associated disorders including insulin resistance, T2D, and NAFLD." (PMID 26124760, 2015). "Very few studies have reported the relationship between MIF gene polymorphisms and obesity." (PMID 25972622, 2015). "Several studies suggest an association between MIF and obesity-induced IR." (PMID 23675368, 2013). "Finally, the identification of prevalent, functional polymorphisms in MIF, which show significant population stratification, prompts closer examination of the contribution of the MIF locus as a risk factor for T2D, obesity, and cardiovascular disease." (PMID 20169173, 2010). "In addition, adipocyte MIF mRNA concentration was also positively associated with adipocytes diameter and independently predicted the peripheral insulin action and the expression of MIF was increased in patients with obesity and diabetes." (PMID 32265835, 2020). "Similarly, increased MIF serum levels were found in overweight adolescents compared with those of normal weight, and MIF concentrations were associated with markers of inflammation and obesity." (PMID 25972622, 2015). "In 3T3-L1 cells, we examined the effects of rTs-MIF on adipocyte differentiation, obesity-related gene expression, and intracellular signaling pathways." (PMID 41596532, 2026). "In this study, we comprehensively evaluated the anti-obesity and anti-inflammatory effects of rTs-MIF at systemic, tissue, and cellular levels." (PMID 41596532, 2026). "Here, we investigated the potential of T. spiralis-derived MIF as a modulator of obesity and evaluated its feasibility as a novel anti-obesity therapeutic candidate with fewer adverse effects by targeting the immune–metabolic axis." (PMID 41596532, 2026).
Obesity (continued). "Given that current anti-obesity drugs are limited by adverse effects, high cost, and the need for long-term administration, rTs-MIF represents a promising new class of anti-obesity candidates that target the immune–metabolic axis." (PMID 41596532, 2026). "In this study, we generated a recombinant form of Trichinella spiralis-derived macrophage migration inhibitory factor (rTs-MIF) and investigated its anti-inflammatory and anti-obesity effects via immunometabolic regulation." (PMID 41596532, 2026). "Macrophage migration inhibitory factor (MIF) is a cytokine involved in inflammatory responses and has been linked to metabolic dysfunction in various conditions, including obesity and diabetes." (PMID 41017289, 2025). "Elevated adipose-derived MIF in obesity and diabetes further impairs insulin signalling and amplifies pro-inflammatory cascades, thereby reinforcing insulin resistance." (PMID 41036138, 2025). "Mice overexpressing MIF, as well as WT mice fed a HFD that caused high circulating MIF levels, showed suppression of HSL, which was associated with the development of obesity." (PMID 37935315, 2024). "Obese individuals often display higher plasma MIF levels compared to their lean counterparts, suggesting a strong correlation between MIF and obesity." (PMID 38802393, 2024). "Although blocking the extracellular action of MIF by a neutralizing MIF antibody successfully reversed HSL down-regulation and reduced obesity in HFD mice, MIF transgenic knockout mice with global loss of MIF action had an opposing effect." (PMID 37935315, 2024). "Plasma MIF levels were found to be significantly increased in patients with obesity compared with healthy donors." (PMID 38175171, 2024). "Plasma MIF significantly correlated with patients’ BMI values of healthy donors and patients with obesity." (PMID 38175171, 2024). "Blocking the extracellular action of MIF by a neutralizing MIF antibody significantly reduced obesity in HFD mice." (PMID 37935315, 2024). "To conclude, the present study showed elevated levels of MMP-9 and MPO and reduced levels of MIF of PWS, which are altered beyond comorbid obesity and clinical cardiovascular risk factors." (PMID 37430349, 2023). "Obesity is also correlated with increased levels of circulating macrophage Migration Inhibitory Factor (MIF) as a result of adipocyte expansion and adipose tissue inflammation." (PMID 38003284, 2023). "CD74 is a type II transmembrane protein, and MIF/CD74 signaling affects M1 macrophage polarization in obesity-related adipose tissue inflammatory disease." (PMID 37431183, 2023). "MIF is a pleiotropic cytokine exerting pro-inflammatory and dysmetabolic functions and exhibiting higher adipose tissue and plasma levels in obesity, insulin resistance, and type 2 diabetes." (PMID 37509065, 2023). "Anti-MIF significantly improved whole-body and adipose insulin sensitivity and attenuated obesity in PD group." (PMID 37283810, 2023). "Obesity suppressed mitophagy, mitochondrial fission and fusion, and mitochondrial biogenesis, and these effects were accompanied by suppression of the MIF/AMPK pathway in the myocardium of mice subjected to fatal stress." (PMID 37711889, 2023). "The tautomerase activity of MIF is notably involved in high-fat diet induced obesity, impacting inflammation." (PMID 38275363, 2023). "In accord with previous paradigms regarding the pathogenesis of obesity, MIF expression in WAT is thought to arise from infiltrating macrophages." (PMID 37283810, 2023). "The macrophage migration inhibitory factor (MIF) expressed in hepatocytes can limit steatosis during obesity." (PMID 36147562, 2022). "MIF actions mainly rely on ERK activation, whose pathway has been involved in the development of insulin-resistance associated with diabetes and obesity." (PMID 33477341, 2021).